CD44 (CD44 molecule (IN blood group))
Diseases named in the same sentence as CD44 in open-access papers (continued):
Sharing a sentence is not in itself a finding about the gene and the disease.
leukemia (continued). "Additionally, CD44 plays crucial roles in pathological processes, particularly in tumor progression, metastasis and chemoresistance, suggesting that it is a potential marker of stem cells in solid tumors and leukemia-initiating cells." (PMID 32347296, 2020). "To determine if CD44 targeting could affect tumour growth in vivo, we used the P245 monoclonal antibody against the CD44 cell surface receptor that was earlier shown to inhibit the development of human leukaemia xenografts." (PMID 19240712, 2009). "These and ancillary observations therefore suggest that overexpression of CD44 may be considered a hallmark of leukemiagenesis and these findings incite the preclinical exploration of immunotherapeutic and CAR-T cell-targeting efficacy of CD44 in diverse experimental leukemia models." (PMID 39980017, 2025). "Mechanistically, through analysis of surface proteins by mass spectrometry, the interactions between CD44-hyaluronic acid and ITGB2-ICAM-1 mediate the targeting of biomimetic vesicles to the bone marrow and leukemia cells, respectively." (PMID 38971796, 2024). "Immunohistochemistry reveals the expression of the stem-cell-related markers CD44 and CD133, which are commonly found in lymphatic tumours and leukaemias." (PMID 37296736, 2023). "Compared with normal VCR molecules, this novel compound displays definite targeting of CD44 + MV4-11 model leukemia cells, which contributes to enhancing its anti-leukemia influence in vitro and obviously improving the therapeutic efficacy in vivo." (PMID 37491290, 2023). "Cancer stem cells (CSCs), initially identified in leukemia in 1994, constitute a distinct subset of tumor cells characterized by surface markers such as CD133, CD44, and ALDH." (PMID 37853437, 2023). "On the contrary, in some cancers such as in leukemia, MMP-2 and MMP-9 bind to CD44 in a complex where MMP-14, interacting with CD44v6, cleaves and activates MMP-2, inducing the degradation of the extracellular matrix." (PMID 33505471, 2021). "A comparison with six sorted pro-B/pre-B samples—the normal cells considered to be closest to ALL blasts—in the oligo(dT) RNA-seq dataset confirmed that CD44 and FLT3 were highly expressed in the hyperdiploid leukemias." (PMID 30944321, 2019). "Taken together, these data suggest that AF1q regulates CD44 expression in CML progenitors, showing a potential mechanism for leukemia stem cell maintenance." (PMID 30154435, 2018). "Therefore we explored, whether a CD44 variant isoform (CD44v)-specific antibody can inhibit leukemia growth without attacking hematopoiesis." (PMID 24684724, 2014). "Previous studies have suggested an interaction between hyaluronan-activated CD44 and CXCL12/CXCR4 signaling in induction of leukemia cell and human umbilical endothelial cell-polarization and subsequent migration." (PMID 24614402, 2014). "It is expressed on many cells, particularly hematopoietic cells including hematopoietic stem cells (HSC), but also leukemia-initiating cells (LIC), where CD44 attracted considerable interest as a functionally important HSC and LIC marker." (PMID 24684724, 2014). "Two mAbs against the CD44 human myeloid marker or the CD45 human leukocyte marker were labeled with Alexa Fluor 750 and administered to leukemia-bearing mice after having verified the immunoreactivity in vitro." (PMID 22303450, 2012). "Notably, several essential genes involved in HSC self-renewal, metabolism, and leukemia development were increased, including GATA2, MSI2, MYCN, CD44, GAS2, HOXB4, and HOXB6." (PMID 38216972, 2024). "Specifically speaking, CD44 enhances VLA-4 activity by inducing intracellular molecular pathways through binding to HA or other extracellular matrices, which in turn enhances the adhesion of leukemia cells to VCAM-1." (PMID 38736891, 2024).
leukemia (continued). "The DKO leukemias also expressed CD25 without CD44, a phenotype that is distinct from that of the majority of E2a-/- leukemias." (PMID 35371057, 2022). "Moreover, accumulating evidence suggests that osteopontin (OPN) enhances IgE-mediated degranulation of mast cells through binding to CD44 and that CD44 can activate the PI3K/Akt and MAPK/ERK pathways in leukemia cells." (PMID 36530573, 2022). "On contrary, the level of CD44 in Tregs-GFP+ co-cultured with TCL1 leukemia cells (but not normal CD19+ cells) was reduced regardless the separation of the cells by transwells." (PMID 35296093, 2022). "In SUP-T1 cells, apart from downregulation of the known BRD4 targets like Myc, Bcl-2, Bcl-XL, and Mcl-1, treatment with ARV-825 substantially decreased the expression of key molecules involved in leukemia persistence, such as HES1 (a direct target of Notch1), PI3K/AKT pathway proteins, and CD44." (PMID 35173274, 2022). "BMSCs can protect leukemia cells against chemotherapy drugs through various cytokines or growth factors (e.g., PDGF, VEGF, EGF, SCF, etc.)or cell-cell surface contact (e.g., SDF1/CXCR4, VLA4/VCAM1, CD44/E-selectin, etc.)." (PMID 34307365, 2021). "In the liver, which is a primary site of leukemia progression in the C1498 model, very few TCRTg101 had proliferated, although a subset began to express CD44, indicating that most TCRTg101 had not yet encountered cognate antigens." (PMID 34758311, 2021). "Another antibody, the humanised mAb (RG7356), was shown to be cytotoxic in chronic lymphocytic leukaemia cells, especially the leukaemia B cells that overexpress CD44, and had little effect on normal B cells." (PMID 34944493, 2021). "Similarly, in AML, CXCR4, CD44, integrins like VCAM1 or VLA-4 are activated upon the contact between AML cells and MSCs to promote resistance of leukemia cells." (PMID 33490067, 2020). "Additionally, E-selectin, the glycoprotein to which leukemia-initiating cells adhere, is upregulated in the bone marrow vasculature in leukemia, thereby encouraging survival signaling and provoking chemoresistance via binding to PSGL-1 and CD44." (PMID 30841639, 2019). "Several genes upregulated in the TF1a dormancy model have been described in leukaemia initiating cells, but appear not to be crucial for maintenance of normal HSCs, e.g. CD44, ITGB3, TIM3 (HAVCR2) and IL3RA." (PMID 29340063, 2017). "It is also important to note that CD44 and VLA-4 receptors expressed by leukemia cells play a role in their adhesion to stromal cells in the niche and the consequent induction of anti-apoptotic effects that support leukemia cell survival." (PMID 24304929, 2013). "The population of memory effector T cells expressing CD44+ and negative for CD62L (TEM) was also significantly more numerous in metastatic tumors stemming from HVEM deficient leukemia cells than in tumors originated from HVEM WT leukemia cells." (PMID 37033927, 2023). "Finally, donor-type CD44+CD8+ effector T cells purified from the GC-treated BM cells expressed granzyme B and mediated equivalent killing on a per-cell basis to the vehicle-treated T cells in redirected cytolysis assays against leukemia cells." (PMID 34637399, 2021). "Furthermore, ampelopsin suppressed the expression of leukemia stemness markers, including Oct4, Sox2, CD44, and CD133, in both cell lines, suggesting that ampelopsin exerts its chemotherapeutic effects by regulating both apoptosis and stemness of leukemia cells." (PMID 33924032, 2021).
leukemia (continued). "While the mechanism of Bcl-2 expression in CSC chemo/drug resistance is still unclear, and it might be due to chromosomal translocation or another pathway, it was demonstrated that leukaemia CD34+ cells expressed Bcl-2 and Bcl-X, and Bcl-2 was highly expressed in breast CD44+/CD24−/low CSCs." (PMID 27825361, 2016). "However, unlike our previous findings, CD44 was not present in resistant leukaemia-derived EVs but only in sensitive EVs." (PMID 26938523, 2016). "It is important to note that CD44 and very late antigen-4 (VLA-4, α4β1-integrin) receptor expressed by leukemia cells govern their adhesion to bone marrow stromal cells in the niche and consequent induction of antiapoptotic effects that support leukemia cell survival." (PMID 27630452, 2016). "However, due to space constraints, this review does not cover the role of CD44 in all aspects of hematopoiesis and leukemia induction; this can be found within an excellent review which also focuses on signal transduction and transcription." (PMID 26074915, 2015). "Previous studies have demonstrated that several adhesion molecules and chemokines, including CXCR4, CD56, CD44, CCR7, and VLA-4, contribute to the harboring and proliferation of leukemic cells in the BM niche and may enhance niche-mediated resistance in leukemia." (PMID 22069486, 2011). "Interestingly, the effects of the antibody were not neutralized in the presence of HA, suggesting that CD44 may have functions other than binding to HA, which play a role in leukemia." (PMID 25954275, 2015). "Similarly, CD44 makes nonmetastatic cells more metastatic probably related to the isoforms that the cell expresses as several CD44v isoforms are cancer stem cell markers in pancreas, laryngeal, head, neck, stomach, colon, lung, breast, ovarian, prostate, glioma, leukemia, or lymphoma cancer." (PMID 33505471, 2021). "In chronic lymphocytic leukemia cells, which express high levels of CD44, a humanized monoclonal antibody specific for CD44 (RG7356) was found to be cytotoxic to leukemia B cells without affecting the viability of normal B cells." (PMID 25954275, 2015). "ARV-825 resulted in reduced BETP-dependent transcription of chemokine receptors, indicated by downregulation of surface CXCR4 and CD44 in leukemia stem cell populations, thereby reducing CD34+CD38– putative leukemia progenitor cell populations without affecting healthy BM–derived progenitor cells." (PMID 33466790, 2021). "This supports the notion that potential protein substrates such as CD45 68, CD43 or CD44 in MLL-r cells could undergo site-specific O-glycosylation events that are absent in normal BCP cells and which could be used as a leukemia-specific marker or target for treatment." (PMID 34646384, 2021).
head and neck squamous cell carcinoma (105 papers, 2008 to 2026). A squamous cell carcinoma that arises from any of the following anatomic sites: lip and oral cavity, nasal cavity, paranasal sinuses, pharynx, larynx, and salivary glands. "An association with CD44 variant isoforms in the progression of head and neck squamous cell carcinoma has been reported." (PMID 27165105, 2016). "The purpose of this study was to examine the expression of the cancer stem cell markers CD133, CD24, CD44, and CD44 variants, in head and neck squamous cell carcinoma." (PMID 24122205, 2014). "Sixty two genes potentially trans-regulated by the lncRNAs such as CD44 (Hyaluronan/CD44 signaling plays an important role in head and neck squamous cell carcinoma progression) and interleukin 1 receptor associated kinase 1 (IRAK1) are involved in the EBV infection pathway." (PMID 32272952, 2020). "The scope of this study was to study the expression of potential cancer stem cell markers CD133, CD24, and CD44, with focus on CD44 exon variants in head and neck squamous cell carcinoma, in order to find attractive molecular targets for selective cancer targeting." (PMID 24122205, 2014). "In this study, the expression of CD44 and its variants was assessed in head and neck squamous cell carcinomas (HNSCC)." (PMID 24122205, 2014). "A CD44-targeted virus-mimicking nanomedicine encapsulating the BMI1 inhibitor PTC209 (PTC209@VNP-HA) was designed to treat head and neck squamous cell carcinoma (HNSCC)." (PMID 40242481, 2025). "Notably, both cervical cancer and head and neck squamous cell carcinoma (HNSCC) frequently exhibit upregulation of CD44, largely driven by the oncogenic activity of high‐risk HPV E6 and E7 proteins." (PMID 40888184, 2025). "CD44V6 is an isoform of the CD44 glycoprotein that is expressed in a variety of malignant tumors, including those of the breast, stomach, and colorectum, as well as head and neck squamous cell carcinoma (HNSCC)." (PMID 41246355, 2025). "For example, a previous study has shown that CD44 is concentrated in tumor cells at the invasive front of head and neck squamous cell carcinomas and promotes metastasis." (PMID 40409554, 2025). "CD44 expression varies amongst different tissues, with certain isoforms being the predominant form in different cancers such as CD44v3 in head and neck squamous cell carcinomas." (PMID 38542115, 2024). "The association between hyaluronic acid (HA) (the ligand of CD44) and CD44 was enhanced by HAS2 in TAMs obtained from patients with head and neck squamous cell carcinoma, as demonstrated by Gomez’s group." (PMID 37211559, 2023). "The aim of the present study was to evaluate the gene and protein expression of CD44 and explore its prognostic value in head and neck squamous cell carcinoma (HNSCC)." (PMID 37593530, 2023). "Tumor cells with high CD44 expression were first reported in HN-CSC in head and neck squamous cell carcinoma with a varying degree of expression intensity." (PMID 37894373, 2023). "For example, positive CD44 head and neck squamous cell carcinoma spheroids showed an increase of 340–750% in invasion compared with negative CD44, which additionally showed resistance to radiotherapy." (PMID 37511533, 2023). "Regulation of MDR1 by CD44 was previously demonstrated in human breast and ovarian tumor cells, as well as in head and neck squamous cell carcinoma (HNSCC)." (PMID 35955749, 2022). "CSCs from head and neck squamous cell carcinoma that were positive for CD44 have reduced MHC-I expression compared with the CD44-negative epithelial cancer cells." (PMID 33613850, 2021). "The functional significance of different CD44 isoforms has been shown in gastrointestinal, prostate, breast, and pancreatic cancer, as well as head and neck squamous cell carcinomas, indicating that the expression of CD44s and CD44v6 is relevant." (PMID 34830890, 2021).
head and neck squamous cell carcinoma (continued). "In head and neck squamous cell carcinoma, a CSC marker CD44 variant was found to directly bind to the cystine/glutamate antiporter xCT, thereby increasing GSH synthesis, which is involved in therapy resistance." (PMID 35155201, 2021). "CD44 has been identified as a potential cancer stem cell marker in head and neck squamous cell carcinoma and its overexpression in pagetoid cells represents a novel treatment target." (PMID 29760516, 2018). "Clinically, CD44 is widely found in head and neck squamous cell carcinoma and is related to worse tumor characteristics and prognosis." (PMID 29693014, 2018). "In head and neck squamous cell carcinoma, PD-L1 is preferentially expressed in CD44+ tumor-initiating cells." (PMID 29250533, 2017). "CD44 is the receptor for hyaluronic acid; in head and neck squamous cell carcinoma, hyaluronan enables CD44 to physically interact with the transcription factors Oct4, Sox2 and Nanog, which are critical determinants of embryonic cell differentiation." (PMID 28098760, 2017). "In head and neck squamous cell carcinoma, PD-L1 is preferentially expressed in CD44+ tumor-initiating cells and inhibits IFN-γ secretion by tumor-infiltrating lymphocytes (TILs) incubated with CD44+ cells." (PMID 29250533, 2017). "MiR-200c expression was significantly reduced in ALDH1+/CD44+ cells with cancer stem cell potency in head and neck squamous cell carcinoma." (PMID 27816053, 2016). "Analogous studies confirmed Bmi1 expression in CD44-positive head and neck squamous cell carcinoma CSCs and in CD49f Sca-1-double positive prostate CSCs." (PMID 26770215, 2016). "Thus, the aim of this study was to evaluate the association of a novel cancer stem cell (CSC) marker, CD44 variant 9 (CD44v9), with cellular refractoriness to chemoradioselection in advanced head and neck squamous cell carcinoma (HNSCC)." (PMID 25751671, 2015). "CD44 is a CSC biomarker that has been identified in head and neck squamous cell carcinoma (HNSCC), in which CD44-positive cells possess the CSC properties of self-renewal and differentiation." (PMID 26202311, 2015). "Similar to these results the cancer stem-cell behavior of CD44-positive cells has also demonstrated in head and neck squamous cell carcinomas." (PMID 23419168, 2013). "Conversely, the use of CD44 as a marker has been questioned due to research suggesting that it is abundantly expressed in head and neck squamous cell carcinomas and that it is equally expressed in normal head and neck epithelium." (PMID 23533441, 2013). "CD44 is a hyaluronan receptor and has been demonstrated to be marker for CSCs in head and neck squamous cell carcinoma (HNSCC)." (PMID 23285037, 2012). "CD44+ plays a major role in studying head and neck squamous cell carcinomas (HNSCC)." (PMID 35800881, 2022). "CD44 is a marker for CSCs and may be a reliable indicator of head and neck squamous cell carcinoma (HNSCC) that can be measured simply and inexpensively." (PMID 33530399, 2021). "A dual gene analysis approach with RNAscope has been utilized for simultaneous detection of CD44+ cells and PD-L1 in head and neck squamous cell carcinoma, which found that CD44+ in the TME induces expression of PD-L1, thus subsequently suppressing T cell-mediated immunity in the TME." (PMID 33917241, 2021). "Glycoproteins such as EGFR, E-cadherin, CD44, PD-1/PD-L1, B7-H3 and Muc1 play important roles in the progression of head and neck squamous cell carcinoma (HNSCC), and their levels of glycosylation and changes in glycosyl structure are closely linked to HNSCC progression and malignant transformation." (PMID 33531990, 2021). "In head and neck squamous cell carcinoma, the following markers have been studied: NFκB-p50, IκB, and the growth factor midkine by blood sampling, and total salivary protein combined with soluble CD44 levels (solCD44) in saliva." (PMID 32670885, 2020).